ALB (albumin)
Diseases named in the same sentence as ALB in open-access papers (continued):
Sharing a sentence is not in itself a finding about the gene and the disease.
tumor (3,102 papers, 1958 to 2026). "Serum albumin, an inexpensive marker associated with systemic inflammation and tumor burden, has shown emerging prognostic potential." (PMID 41682996, 2026). "In patients with BTC (n = 221), the preoperative albumin concentration was associated with tumor resectability at the group level (p = 0.025), but not in subgroup analysis according to gender." (PMID 41504962, 2026). "An elevated inflammatory response to tumor cells and an increased release of a variety of cancer-related cytokines that are implicated in tumor initiation are associated with a reduced serum albumin level (Oymak, Guler & Onal, 2023)." (PMID 41522516, 2026). "In other studies, various tumor parameters, such as size or vascular invasion, were associated with albumin levels below 30.5 mg/dL, suggesting that lower albumin levels were correlated with more aggressive tumors, thereby indicating a poorer prognosis." (PMID 41157241, 2025). "Univariate logistic regression identified several factors, including tumor size > 4 cm, open surgery, greater intraoperative blood loss, low postoperative albumin, low SMI, high VATI, and low PNI, as risk factors for complications ≥G2." (PMID 41568386, 2025). "The higher CRP/albumin ratio was associated with tumor progression, high CLIP and BCLC scores, and decreased liver function reserve." (PMID 40181742, 2025). "OF these factors, high AFP, albumin levels, tumor diameter, high blood loss, high CNLC stage, high ALICE-CNLC stage, high BCLC stage, and high ALICE-BCLC stage were all found to be independently linked with RFS." (PMID 40052123, 2025). "Inflammation caused by the tumor and cancer cachexia is associated with myosteatosis and serum albumin levels." (PMID 41002580, 2025). "Lower levels of albumin in cancer patients have been linked to poorer prognosis, possibly because reduced antioxidant capacity allows for increased oxidative damage and tumor progression." (PMID 40719999, 2025). "Univariate Cox regression analysis revealed that higher Child-Pugh scores, lower levels of serum ALB and recurrent tumor were associated with increased risk of PFS, while responder based on RECIST 1.1 and mRECIST acted as protective factors for PFS." (PMID 40666526, 2025). "PG-SGA score, serum albumin concentration, hemoglobin concentration, operation time, tumor stage, and previous abdominal surgery are independent risk factors for PPOI." (PMID 40271430, 2025). "The BALAD-2 model incorporates continuous values of AFP, AFP-L3%, DCP, albumin, and bilirubin, providing a nuanced risk assessment that reflects both tumor biology and hepatic functional reserve." (PMID 41228250, 2025). "Although albumin is widely recognized for its role in maintaining colloid osmotic pressure and regulating plasma volume, recent studies have implicated it in tumor progression, invasion, and metastasis." (PMID 41008815, 2025). "Biologically, ALB reflects nutritional status and systemic inflammation, while monocytes are implicated in immune suppression, angiogenesis, and tumor progression; together, they integrate key dimensions of host–tumor interaction that shape clinical outcomes." (PMID 41155750, 2025). "These together implicated possible tumour initiation or promotion roles of ALB+KRT7+ EPCs‐derived ALD organoids." (PMID 39834100, 2025). "TACE for HCC in patients with serum albumin ≤ 3.8 g/dL, PT ≤ 80%, and largest tumor diameter ≥ 3.8 cm is likely to cause deterioration of the Child‐Pugh classification, leading to delayed introduction of systemic therapy." (PMID 39487694, 2024). "Most studies have shown possible relationships between chronic, systemic inflammatory responses caused by low serum albumin levels, impaired cellular immune response, and tumor cachexia." (PMID 39596977, 2024). "As PNI is intricately linked with serum albumin and peripheral blood lymphocyte count, it serves as a reflection of the delicate balance between inflammation and immune response within the tumor microenvironment." (PMID 39624124, 2024).
tumor (continued). "Low ACR was significantly associated with advanced age; T, N, and M stages; larger tumor diameter; low albumin levels; and high CEA levels." (PMID 39897534, 2024). "The anti-albumin-linked construct provides a means for the rIL12 protein to maintain a tumor-specific, efficacious, therapeutic concentration over an extended period, while decreasing potential toxicity and contributing to the drug’s safety." (PMID 39697343, 2024). "Univariate analysis revealed that gender, the number of comorbidities, postoperative serum albumin, tumor location, duration of operation were risk factors associated with EJAL." (PMID 39669366, 2024). "According to our data, the addition of albumin caused significant dose-dependent inhibition of NK–tumor cell conjugation in both conditions." (PMID 38646521, 2024). "The tumor size, use of plastic reconstructive techniques, duration of the surgery, ligation of iliac vessels, and serum albumin levels were associated with postoperative wound-related compilations, while surgical margins were associated with local recurrence." (PMID 38473334, 2024). "The results of the univariate analysis of patient and tumor characteristics showed that the pretreatment Child–Pugh score and albumin–bilirubin (ALBI) Grade were significant risk factors for RILD." (PMID 38649902, 2024). "Univariate analysis showed that gender, postoperative serum albumin, and tumor location were associated with EJAL." (PMID 39669366, 2024). "In MM, ALB level is also thought to reflect the damage to the liver caused by interleukin-6 produced in the tumor microenvironment." (PMID 39640278, 2024). "Highly abundant plasma proteins like albumin can mask the detection of low abundant EV proteins in MS, such as tumor-associated proteins." (PMID 39190201, 2024). "Both fibrinogen ≥ 4.46 g/L (OR 2.93, 95% CI [1.53–5.63], p = 0.001) and albumin ≤ 39.9 g/L (OR 3.00, 95% CI [1.56–5.76], p = 0.001) were also associated with a lower rate of complete tumor resection after primary cytoreductive surgery." (PMID 39409916, 2024). "Within the context of the tumor microenvironment, it has been observed that the tumor exhibits a rapid uptake of albumin as a compensatory response to the relatively deficient availability of amino acids." (PMID 38169970, 2024). "Here we took on the unique goal of constructing a library of siRNA-lipid conjugates in an effort to identify lipid siRNA conjugate structural features that promote preferential in situ albumin association and functional tumor delivery in vivo." (PMID 38383524, 2024). "Tumor diameters>5cm, microvascular invasion and albumin level<35 g/L were independent risk factors for early recurrence." (PMID 39286273, 2024). "After adjusting for age, sex, ascites, tumor characteristics (size, number, distribution), and liver function parameters (ALB, AFP, AST, and TBIL), the association remained significant, with an adjusted HR of 5.96 (95% CI: 3.39–10.5; P < 0.001)." (PMID 39902133, 2024). "Tumor diameter>5 cm, microvascular invasion, and albumin level<35 g/L were independent risk factors for early recurrence." (PMID 39286273, 2024). "Serum fibrinogen and albumin play important roles in systemic inflammation and are implicated in tumor progression." (PMID 39400724, 2024). "The non-specific fluorescence of cyanine dyes caused by interference from albumin is a commonly encountered problem 35, particularly in tumor localization where it can significantly affect the accuracy and contrast of targeted probes." (PMID 38773981, 2024). "Known covariates, such as high serum albumin concentration as well as investigational covariates, such as high eosinophil levels were associated with longer OS in all tumor types." (PMID 37962239, 2023). "Albumin has been approved to play an inhibitory role in systemic inflammation and cause the tumor progression." (PMID 37015898, 2023).
tumor (continued). "Most studies have shown possible relationships between chronic, systemic inflammatory response, compromised cellular immune response, and tumour cachexia caused by low serum albumin levels." (PMID 38132403, 2023). "Alternatively, a secreted protein acidic and rich in cysteine (SPARC) can sequester albumin in the tumor stroma and is partially associated with the tumor-specific albumin uptake." (PMID 37836018, 2023). "Albumin has been linked to tumor necrosis because pro-inflammatory cytokines reduce albumin production." (PMID 36875852, 2023). "Albumin was reported to have a potential role in inhibiting the HCC growth; thus, lower albumin was associated with larger tumor diameters, more tumor multifocality, and higher AFP levels." (PMID 38138039, 2023). "Meanwhile, the reduction of albumin level is also associated with worse nutritional status of the body, leading to a decrease in immune function and, subsequently, tumor recurrence." (PMID 36369395, 2023). "Albumin can potentially carry a high amount of active antitumor compounds to the tumor site via albumin association." (PMID 36441260, 2023). "The albumin produced by hepatocytes is associated with nutritional status and increased inflammatory response to the tumor." (PMID 36511609, 2023). "The tumor number, serum albumin level, and DCP level, which are well-known risk factors for HCC recurrence, were found to be the most important variables." (PMID 39129938, 2022). "Subgroup analyses across several tumor types demonstrated a consistently higher risk of death in patients with lower albumin levels than in patients with higher albumin levels." (PMID 36533070, 2022). "Whereas IL-6 was associated with albumin values and had a tendency to be higher in patients with worse performance status and larger tumors, IL-8 was associated with tumor diameter and partly correlated with bilirubin values." (PMID 33855585, 2022). "In univariate Cox regression analysis, high SIII, low albumin levels, positive lymph node status, R1 margin status, higher T stage, poor tumor differentiation, tumor location, high ASA-score, and high CA19-9, were associated with shorter disease-free survival." (PMID 35296013, 2022). "Chronic inflammation and tumor progression can increase albumin degradation and catabolism, both decreasing the functional capability of albumin as well as causing an overall decrease in total circulating albumin." (PMID 35406456, 2022). "Tumour diameter greater than three centimetres, multifocal tumour disease, vascular invasion, preoperative low albumin and increased alpha-fetoprotein (AFP) values were associated with significantly worse OS." (PMID 36233670, 2022). "In a subsequent Cox regression analysis, high albumin, high bilirubin, large tumor size prior to TACE and the BCLC stage were associated with impaired survival." (PMID 35016731, 2022). "Even though pre-albumin and Fibrinogen are all widely acknowledged to be associated with tumor prognosis, the Fibrinogen to pre-albumin ratio (FPR) has rarely been reported to evaluate the prognosis of patients with digestive tumors." (PMID 35033080, 2022). "Complications were significantly associated with incomplete R2 resection, tumor size >10 cm and low preoperative albumin levels." (PMID 35267600, 2022). "Various blood examination-based nutritional parameters have been implicated in tumor prognosis (prognostic nutritional index, albumin-globulin ratio and c-reactive protein to albumin ratio)." (PMID 35729545, 2022). "Tumor accumulation of Abraxane® is favored by the overexpression of the secreted protein acidic and rich in cysteine (SPARC) in the membrane of the tumor cell, associated with albumin arrest in the microenvironment." (PMID 36015347, 2022). "For this reason, ABPs can act as a target for drugs with albumin coating and cause more drug uptake by tumor cells." (PMID 36359230, 2022).
tumor (continued). "While the serum albumin level is used to assess the nutritional status and immune function, a reduced albumin level is associated with tumor progression, metastasis, and increased risk of death after surgery." (PMID 35715991, 2022). "After intravenous administration,the maleimide on the side chain can rapidly bind to endogenous albumin,enabling the prodrugs to accumulate in tumors, where tumor-associatedhypoxia microenvironments trigger the selective release of Exatecan." (PMID 35036771, 2022). "Independent prognostic factors associated with OS identified in previous studies were albumin, alpha-fetoprotein, alkaline phosphatase and tumour size <5 cm." (PMID 36593888, 2022). "The prognostic factor (RAS mutation) and other tumor markers (e.g. fibrinogen/albumin index or prognostic nutrition index, etc.)were also not available." (PMID 35570841, 2022). "The parameters included in point assigning were tumor number and size, alpha-fetoprotein, albumin, bilirubin, vascular invasion, cause, and response, as assessed by mRECIST criteria." (PMID 35330436, 2022). "Serum albumin is associated with activated systemic inflammation during tumor proliferation and invasion." (PMID 36458178, 2022). "Large tumor size and high albumin level were identified as risk factors for postoperative variceal formation at 3 and 6 mo, respectively." (PMID 35634189, 2022). "Another study indicates that a low albumin-to-fibrinogen ratio to be associated with higher tumor size and stage." (PMID 36579608, 2022). "Low serum albumin levels means the presence of cancer cachexia is caused by a sustained inflammatory response, either from the tumor itself or as a host reaction." (PMID 36132141, 2022). "In univariable analyses, ECOG PS, tumor stage, SpVT-related symptoms, clinical situation at the time of diagnosis of SpVT, albumin level, and hemoglobin level were associated with OS after the diagnosis of SpVT (P < 0.05)." (PMID 35041664, 2022). "Among them, gender, diameter of the tumor, post-recurrence adjuvant treatment, serum albumin and hemoglobin showed the association with outcomes." (PMID 34445989, 2021). "In our study, younger age, low serum albumin level, general anesthesia, larger tumors, and higher tumor number were the independent factors associated with post-RFA fever in the multivariate analysis." (PMID 34771466, 2021). "In the present study, we evaluated the relationship of clinicopathological characteristics and the long-term prognosis of 468 ICC patients, and found that the PLR and the ALB, two non-tumor-specific SIR markers, were significantly associated with OS." (PMID 33676467, 2021). "The salient finding of this study is the association of urinary IGFBP-7 with renal impairment and tumor burden (marked by FLCs, albumin, β2-microglobulin)." (PMID 34946293, 2021). "The content of albumin encoded by ALB has been confirmed to be closely related to tumor development and patient prognosis." (PMID 34603396, 2021). "Risk factors for OS include serum albumin concentration, tumor diameter, tumor stage III, and poor differentiation, and risk factors for RFS include vascular invasion, tumor stage III, and poor differentiation." (PMID 35155212, 2021). "Although univariate analysis showed that albumin, prothrombin time, alpha-fetoprotein level, Child-Pugh score, and lipiodol deposition in tumor were associated with OS, multivariate analysis showed that none of them was an independent prognostic factor for OS." (PMID 33738247, 2021). "This study revealed that tumor height and albumin were independent risk factors associated with iCSF leakage." (PMID 34765541, 2021). "A higher level of serum creatinine, lower level of serum albumin, larger tumor size, and the presence of varix were associated with shorter OS." (PMID 34885118, 2021).
tumor (continued). "Mutations with high levels of albumin and globulin means that the proliferation and secretion of tumor cells are more vigorous, which indirectly means more tumor cells and smaller intercellular spaces." (PMID 34103001, 2021). "Variables related to the tumor (disease stage), pharmacokinetics (renal function and albumin), nutritional status (weight loss and albumin) and comorbidities (Charlson comorbidity score) correlated with UH." (PMID 35008291, 2021). "Inflammation is also an important regulator of tumor progression through suppression of albumin synthesis, recruitment of T lymphocytes and tumor-associated macrophages, and upregulation of angiogenic growth factors." (PMID 33816284, 2021). "Confocal microscopy analysis underlined that our albumin NPs are readily internalized in tumor cells with nuclear localization." (PMID 35582009, 2021). "Para-vessel lesions was the only risk factor for LTP, whereas age, previous treatment, Albumin-Bilirubin score, and tumor diameter were risk factors for RFS." (PMID 33675382, 2021). "We demonstrated that when younger people with a low serum albumin level underwent general anesthesia, the tumor numbers and tumor sizes were associated with a higher rate of post-RFA fever." (PMID 34771466, 2021). "Tumor size at baseline, sex, and albumin presented the strongest association with V1, while age was the most influential covariate on V2." (PMID 33145616, 2021). "Univariate analysis showed that the Child-Pugh score, MELD score, platelet count, total bilirubin, serum albumin, sodium, maximum tumor diameter, and initial treatment modality were associated with survival rate." (PMID 33996606, 2021). "Cox regression analysis of risk factors revealed that preoperative serum albumin and type primary tumour were independent risk factors for mortality." (PMID 32245389, 2020). "Patients with low serum albumin levels are associated with poor nutritional and immune status, which can be a favorable condition for tumor invasion and metastasis." (PMID 32219033, 2020). "The significant risk factors for overall survival after TACE were serum albumin level, bilobar tumor location, tumor stage, and AKI stage." (PMID 33315944, 2020). "The factors influencing survival were tumor number and size, alpha‐fetoprotein, albumin, bilirubin, vascular invasion, cause, and response as assessed by mRECIST." (PMID 31698504, 2020). "Specifically, this inflammation involves an increased activity of neutrophils and lymphocytes which secrete factors associated with tumor progression, such as C-reactive protein and albumin." (PMID 33276524, 2020). "When injected intratumorally into EMT6 tumor bearing mice, the MnO2-Albumin NPs caused 45% increase in saturated O2 levels at tumor periphery compared to mice without NP treatment." (PMID 33240859, 2020). "This study indicated that serum albumin level, tumor stage, bilobar location of tumor, and AKI stage significantly associated with overall survival in HCC patients who underwent TACE." (PMID 33315944, 2020). "It includes variables, such as anaesthetic risk and other analytical variables (albumin, creatinine), together with some relating to the extent of the tumor and indications for surgery." (PMID 32545670, 2020). "Due to the elevated capillary loss rates of small molecules in enhancing tumor, Gd-DTPA tumor coverage is much lower than that of albumin for both sets of patients." (PMID 32967184, 2020). "The risk of tumor progression was 4 times greater in the patients with high fibrinogen and low albumin levels, and the risk of mortality was 4.23 times greater in such patients." (PMID 32257553, 2020). "We found that pathological T stage, age at diagnosis, length of tumor, and albumin level were likely to be associated with SCC-Ag level (all P < 0.05)." (PMID 32456707, 2020). "Preoperative serum albumin level and primary tumour site are independent risk factors of survival in patients treated for pathological femur fractures." (PMID 32245389, 2020).